METTL14 (methyltransferase 14, N6-adenosine-methyltransferase non-catalytic subunit)
Diseases named in the same sentence as METTL14 in open-access papers (continued):
Sharing a sentence is not in itself a finding about the gene and the disease.
diabetes (12 papers, 2021 to 2026). "Our investigations provide an extensive reference for future discussions on the molecular mechanism underlying METTL14 in diabetes." (PMID 40299682, 2025). "Lentivirus-mediated upregulation of Mettl14 attenuated diabetes-associated heart dysfunction by augmenting the m6A RNA methylation of long noncoding RNA (lncRNA) TINCR and subsequently suppressing pyroptosis through inhibition of NLRP3 mRNA expression." (PMID 38706718, 2024). "We also examined METTL14 expression in blood samples from 20 people with diabetes before and after intensive insulin therapy." (PMID 40299682, 2025). "We have reported that the deletion of Mettl14 in postnatal pancreatic β-cells leads to fewer β-cells and the development of diabetes in mice." (PMID 39322760, 2024). "In our previous study, we reported that deletion of Mettl14 in postnatal pancreatic β-cells leads to changes in the identity and numbers of β-cells and the development of diabetes after birth in mice." (PMID 39322760, 2024). "β‐cell–specific METTL14 knockout mice exhibited reduced β‐cell proliferation, insulin degranulation, and early‐onset diabetes, similar to those with human T2DM." (PMID 36891946, 2023). "This suggests that METTL14 might influence insulin signaling transduction to enhance diabetes by regulating the expression of TPK1, IPMK, and PIK3R1." (PMID 40299682, 2025). "METTL14 has demonstrated its ability to control β-cell function and diabetes mellitus." (PMID 40299682, 2025). "This suggests that METTL14 might serve as a biomarker for diabetes treatment." (PMID 40299682, 2025). "In patients with type 2 diabetes (T2D), m6A levels were reduced, while the mRNA levels of FTO, METTL3, METTL14, WTAP were significantly elevated and involved in the pathogenesis of diabetes." (PMID 34026872, 2021). "Further investigation of older mice (2 months of age) showed that depletion of Mettl14, regardless of the timing of Mettl14 depletion during pancreas development, lead to the development of diabetes in Pdx1CreM14KO, Ngn3CreM14KO and Ins1Cre M14KO mice." (PMID 39322760, 2024). "Similarly, it is reported that METTL3, FTO, METTL14, and WTAP are up-regulated in diabetes patients." (PMID 33748197, 2021).
ovarian carcinoma (12 papers, 2019 to 2025). A malignant neoplasm originating from the surface ovarian epithelium. "The METTL14 loci carried synaptopodin 2 (SYNPO2), where a mutation looped between the first intron of this gene and the METTL14 promotor was linked to increased susceptibility to ovarian cancers in humans." (PMID 39596561, 2024). "The cells were then treated with or without actinomycin D for various assays to understand the in vivo and in vitro regulatory roles of METTL14 in ovarian cancer as well as the underlying molecular events." (PMID 35251990, 2022). "Among the 10 key m6A RNA methylation regulators, the GEO data only showed a reduction in the METTL14 mRNA levels in the ovarian cancer tissues, which was associated with a lower METTL14 copy number." (PMID 35251990, 2022). "Furthermore, reduced METTL14 expression was associated with alterations in CNVs as well as poor patient survival in ovarian cancer." (PMID 35251990, 2022). "Although we have observed that FSH decreased METTL14 expression, the 'reader' of m6A, the role of METTL14 in EMT of ovarian cancer remains to be investigated." (PMID 38505602, 2024). "Through further analysis of the comparative genomic hybridization data using high-resolution microarrays, we found lower METTL14 copy numbers in ovarian cancer tissues than in normal ovarian tissues." (PMID 35251990, 2022). "Since METTL14 had a profound impact on ovarian cancer cell proliferation, we reasoned that the specific genes regulated by METTL14 should predominantly function in this process." (PMID 35251990, 2022). "Immunohistochemical analysis of the METTL14 expression pattern using the ovarian cancer tissue array was consistent with the online database data, showing reduced METTL14 expression in ovarian cancer tissues." (PMID 35251990, 2022). "We transfected ovarian cancer SKOV-3 and A2780 cells with a METTL14 expression vector or Trophinin associated protein (TROAP) siRNA." (PMID 35251990, 2022). "Based on our analysis of m6A methylation regulators using The Cancer Genome Atlas (TCGA) and Gene Expression Omnibus (GEO) datasets, we focused on the regulatory role of METTL14 in ovarian cancer." (PMID 35251990, 2022). "We performed bioinformatics and survival analyses with these datasets and also used METTL14-overexpressing SKOV-3 ovarian cancer cells for in vitro studies." (PMID 35251990, 2022). "Further in vivo and in vitro experiments confirmed that METTL14 is a negative regulator of ovarian cancer cell proliferation via TROAP expression and that m6A RNA methylation regulates TROAP mRNA stability." (PMID 35251990, 2022). "Among these regulators, METTL14, which is an m6A mRNA methylation writer, also exhibited reduced expression levels and subsequent low levels of m6A methylation in ovarian cancer." (PMID 35251990, 2022). "We transduced SKOV-3 cells with the lentivirus containing the METTL14 expression vector to evaluate the effect of METTL14 overexpression on the regulation of ovarian cancer cell proliferation in vitro." (PMID 35251990, 2022). "We further demonstrated that METTL14 inhibited the expression of TROAP via the m6A RNA modification in ovarian cancer cells, which also inhibited cell proliferation by suppress cyclin D1, survivin, and p-AKT." (PMID 35251990, 2022). "Similar to these findings, our current data showed that METTL14 had a significant reduction in CNVs in ovarian cancer tissues and that METTL14 overexpression inhibited ovarian cancer cell proliferation in vitro, further confirming the TCGA and GEO data." (PMID 35251990, 2022). "The results of our study provide important insights into the m6A RNA modification by METTL14 in the regulation of ovarian cancer." (PMID 35251990, 2022). "Altogether, these data suggest that METTL14 functions as a negative regulator of TROAP in ovarian cancer cells and tissues." (PMID 35251990, 2022).
ovarian carcinoma (continued). "Our results showed that METTL14 overexpression significantly elevated the rate of m6A RNA methylation in ovarian cancer SKOV-3 cells." (PMID 35251990, 2022). "Because the loss of WTAP significantly blocks the m6A RNA modification process, we knocked down WTAP with siRNA in METTL14-overexpressing cells to evaluate the effects on ovarian cancer cell proliferation." (PMID 35251990, 2022). "In conclusion, METTL14 overexpression decreased ovarian cancer proliferation by inhibition of TROAP expression via an m6A RNA methylation-dependent mechanism." (PMID 35251990, 2022). "To confirm the function of METTL14 in ovarian cancer in vivo, we used the SKOV-3 cells with stable overexpression of METTL14 or control for establishing xenograft model." (PMID 35251990, 2022). "Restoration of METTL14 expression suppresses ovarian cancer cell proliferation by inhibition of TROAP expression." (PMID 35251990, 2022). "In the study, METTL14 was lowly expressed in ovarian cancer samples and highly expressed in patients of Stage 1/2 subgroup and correlated with OC prognosis; thus, it is clear that the same M6A regulator also exerted different effects in different tumors." (PMID 34187307, 2021). "METTL14-catalyzed m6A modification is markedly reduced in ovarian carcinoma tissues, and reinstatement of METTL14 expression may attenuate ovarian cancer cell proliferative capacity by repressing trophinin-associated protein (TROAP) levels." (PMID 40986143, 2025). "Taken together, these data suggest that METTL14 may function as a negative regulator of ovarian cancer cell proliferation via inhibition of TROAP and its downstream targets." (PMID 35251990, 2022). "We postulated that the METTL14-TROAP axis may be responsible for the regulation of ovarian cancer cell proliferation." (PMID 35251990, 2022). "Moreover, the METTL14 and m6A RNA methylation levels were both significantly reduced in ovarian cancer tissues than in normal tissues." (PMID 35251990, 2022). "We then transfected exogenous TROAP into the METTL14-overexpressing ovarian cancer cells." (PMID 35251990, 2022). "Based on these analyses, we decided to focus on METTL14 in ovarian cancer tissues and cells." (PMID 35251990, 2022). "Therefore, our results indicated that METTL14 inhibited the proliferation ability of human ovarian cancer cells in vitro and in vivo." (PMID 35251990, 2022). "The similar results of colony formation assay and flow cytometry in A2780 cells further suggest that METTL14 may function as a negative regulator of ovarian cancer cell proliferation." (PMID 35251990, 2022). "Besides, there was a reduction (~34%) of METTL3 mRNA expression but unchanged METTL14 mRNA expression in ascites NK cells of ovarian cancer patients." (PMID 34535671, 2021). "It has been reported that METTL3 and METTL14 were downregulated in ovarian carcinoma cells." (PMID 34745970, 2021). "To further verify whether METTL14-induced downregulation of TROAP expression is dependent on m6A mRNA methylation in ovarian cancer tissues and cells, we assessed the m6A methylation rate in ovarian cancer cells after transfection with the METTL14 expression vector." (PMID 35251990, 2022). "Ultimately, our findings confirm that EZMLD induces apoptosis in ovarian cancer cells through the mechanism of METTL3 and METTL14 methyltransferases, which mediate KRT8 m6A methylation modification." (PMID 39103890, 2024). "METTL14 targeted TROAP mRNA through m6A modification to reduce stability, thus inhibiting cell proliferation and suppressing the proliferative capacity of ovarian cancer cells in vitro and in vivo." (PMID 37194218, 2023). "In summary, the current study delineates that METTL14 negatively regulates TROAP expression in an m6A RNA methylation-dependent manner and that its expression is reduced in ovarian cancer and promotes cancer cell proliferation." (PMID 35251990, 2022).
ovarian carcinoma (continued). "Levels of the m6A methylase “writers,” including METTL3, METTL14 and WTAP, were increased in brain, central nervous system (CNS), cervical, and head and neck cancer and sarcoma but decreased in BC, lymphoma and ovarian cancer as compared with normal controls." (PMID 30953473, 2019). "Indeed, METTL3, METTL14, and FTO have been clarified to affect the progression of ovarian cancer in a m6A-dependent manner." (PMID 39617776, 2024). "METTL14 can assist METTL3 in substrate recognition and expressed at low levels in ovarian cancer." (PMID 37194218, 2023). "Therefore, we first assessed the METTL14 m6A methyltransferase levels using the GEO database (GSE119168) and found its levels to be significantly decreased in ovarian cancer tissues." (PMID 35251990, 2022). "METTL3 and METTL14 form a stable heterodimer to affect the metastatic potential of cancer cells via distinct mechanism, for example, METTL3 promoted the initiation and metastasis of ovarian cancer by inhibiting CCNG2 expression." (PMID 35869392, 2022). "However, there are currently no previous reports on the role of METTL14 in ovarian cancer; thus, further studies are warranted." (PMID 35251990, 2022). "No change of global m6A levels in ovarian cancer resistant cells might be due to downregulated FTO, ALKBH5, METTL3, and METTL14." (PMID 34745970, 2021).
prostate carcinoma (12 papers, 2020 to 2025). A carcinoma that arises from epithelial cells of the prostate gland. "Importantly, IGF2BP3, HNRNPA2B1, and METTL14 were significantly associated with RFS of prostate cancer in multivariable cox regression established on mRNA expression of m6A methylation regulators." (PMID 32710725, 2020). "The expression of METTL3 and METTL14 also significantly increased in castration-resistant prostate cancer." (PMID 37701836, 2023). "In vitro experiments confirmed that upregulation of METTL14, an m6A writer, enhanced the invasion, metastasis, and sensitivity of prostate cancer cells to poly (ADP-ribose) polymerase inhibitor." (PMID 35814454, 2022). "METTL14 upregulation was found to be closely correlated with the recurrence‐free survival of prostate cancer." (PMID 34904301, 2022). "Specifically, METTL14 overexpression elevates the m6A modification level of mRNA and enhances the advancement of prostate cancer by managing the localization of subcellular proteins." (PMID 34904301, 2022). "This phenomenon suggests that METTL3 and METTL14 exerted as a complicated regulator in prostate cancer." (PMID 34531875, 2021). "It was found that the expression of METTL14, IGF2BP3, HNRNPA2B1, and CNV of ALKBH5 were linked to the recurrence-free survival of prostate cancer." (PMID 34899855, 2021). "In this study, we first found METTL14 was highly expressed in the normal samples in prostate cancer patients, and insignificantly associated with GS and RFS of prostate cancer." (PMID 32710725, 2020). "We presented IGF2BP3, HNRNPA2B1 and METTL14 were significantly related to RFS of prostate cancer based on mRNA expression information, while in the CNV-based regression model, YTHDF2, FTO, and ALKBH5 were notably associated with prognosis of prostate cancer." (PMID 32710725, 2020). "To confirm our funding, we added critical clinical characteristics such as diagnosed age, GS, tumor T stage and N stage, the three m6A methylation regulators (IGF2BP3, HNRNPA2B1, and METTL14) were still remarkably related with prognosis of prostate cancer." (PMID 32710725, 2020). "In prostate cancer, m6A modification level was upregulated, and the expression levels of METTL3, METTL14, VIRMA, RNA binding motif protein 15 (RBM15), HNRNPC, HNRNPA2B1, YTHDC2, YTHDF1 and YTHDF2 increased." (PMID 37701836, 2023). "The expression of METTL3, METTL14, WTAP, and CBLL1 was higher in prostate cancer cells compared to non-malignant prostate cells." (PMID 36835633, 2023).
osteoporosis (10 papers, 2021 to 2025). A condition of reduced bone mass, with decreased cortical thickness and a decrease in the number and size of the trabeculae of cancellous bone (but normal chemical composition), resulting in increased fracture incidence. "The expression of METTL14 mRNA decreased in the alveolar bone of postmenopausal women with osteoporosis (P11–P20) according to RT‐qPCR analysis." (PMID 40051055, 2025). "Studies have shown that the expression levels of METTL3 and METTL14 are significantly decreased in the bone tissue of osteoporosis patients." (PMID 39779466, 2025). "Decreased methylation levels and lower expression of METTL3/METTL14 were revealed in osteoporosis-BMSCs than in BMSCs from the control group." (PMID 38665846, 2024). "Cell fate of BMSCs in mice is disrupted by METTL3 or METTL14 deletion, leading to osteoporosis pathological characteristics including decreased bone mass and accumulated marrow adiposity." (PMID 38665846, 2024). "Deng and colleagues found that METTL14 was downregulated in postmenopausal osteoporotic women and overexpression of METTL14 can suppress osteoclast formation to ameliorate osteoporosis by stabilizing GPX4." (PMID 38355483, 2024). "It was discovered that the expression of METTL3 and METTL14 and the overall m6A level were decreased in the bone tissues of three patients with osteoporosis." (PMID 37202385, 2023). "Next, exosomes were used as carriers for osteoporosis correction in vivo, which can transport METTL14 into osteoclasts." (PMID 37957146, 2023). "Our results showed that the METTL14 protein levels, METTL14 mRNA levels, and m6A content in total RNA were lower in osteoporosis patients (T ≤ −2.5) than in control patients (T ≥ −2.5)." (PMID 33440070, 2021). "Collectively, our results highlight the critical roles of the miR‐103‐3p/METTL14/m6A signaling axis in osteoblast activity, identifying this axis as a potential target for ameliorating osteoporosis." (PMID 33440070, 2021). "Deng found that the expression of METTL14 was decreased in postmenopausal patients with osteoporosis, and overexpression of METTL14 could stabilize GPX4 mRNA and inhibit osteoclast differentiation and bone absorption." (PMID 40051055, 2025). "Consistent results for METTL3 and METTL14 were obtained in osteoporosis animal models." (PMID 38665846, 2024). "In conclusion, interference with METTL14 inhibited osteogenic differentiation of BSMCs by m6A modification of SMAD1 in an IGFBP1 manner, suggesting that METTL14 might be a novel approach for improving osteoporosis." (PMID 36319624, 2022). "Consequently, METTL3 and METTL14 may serve as potential targets for osteoporosis treatment." (PMID 39779466, 2025). "However, the biological significance of the m6A methyltransferase METTL14 in bone formation or osteoporosis has not been confirmed." (PMID 33440070, 2021).
colon cancer (9 papers, 2020 to 2025). "METTL14 limits malignant progression of colon cancer by inhibiting the lncRNA XIST." (PMID 32793593, 2020).